B3GALT2 (beta-1,3-galactosyltransferase 2)
Description:
Beta-1,3-galactosyltransferase that transfers galactose from UDP-galactose to substrates with a terminal beta-N-acetylglucosamine (beta-GlcNAc) residue. Can also utilize substrates with a terminal galactose residue, albeit with lower efficiency. Involved in the biosynthesis of the carbohydrate moieties of glycolipids and glycoproteins. Inactive towards substrates with terminal alpha-N-acetylglucosamine (alpha-GlcNAc) or alpha-N-acetylgalactosamine (alpha-GalNAc) residues.
Synonyms: Beta3Gal-T2; Beta3GalT2; GLCT2
Tractability: Antibody: UniProt predicts a signal peptide or a membrane-spanning region; the Human Protein Atlas places it where antibodies can reach.
Gene: Protein-coding gene on chromosome 1 (193,178,730 to 193,186,613, reverse strand). Ensembl gene ENSG00000162630.
Subcellular location: Golgi apparatus membrane
Subcellular location (Human Protein Atlas): Plasma membrane
Pathways (Reactome):
Metabolism: Lewis blood group biosynthesis
Gene Ontology:
Molecular function: N-acetyl-beta-D-glucosaminide beta-(1,3)-galactosyltransferase activity; protein binding; hexosyltransferase activity
Biological process: glucosylceramide metabolic process; glycoprotein biosynthetic process; oligosaccharide biosynthetic process; carbohydrate derivative metabolic process
Cellular component: Golgi membrane; membrane
Genetic constraint (gnomAD): Loss-of-function variants: 13 observed, 35.18 expected, observed/expected ratio (o/e) 0.37, 90% interval 0.24 to 0.59. The upper end of that interval is the gene's LOEUF score, 0.59, which puts it in group 2 of 6, group 1 being the genes least tolerant of losing a copy. Missense variants: 418 observed, 532.59 expected, observed/expected ratio (o/e) 0.78, 90% interval 0.72 to 0.85. Synonymous variants: 195 observed, 183.19 expected, observed/expected ratio (o/e) 1.06, 90% interval 0.95 to 1.2.
Homologues: Orthologues: macaque B3GALT2 (99% identical), dog B3GALT2 (99% identical), chimpanzee B3GALT2 (98% identical), guinea pig B3GALT2 (98% identical), rat B3galt2 (96% identical), rabbit B3GALT2 (96% identical), pig B3GALT2 (95% identical), mouse B3galt2 (95% identical), tropical clawed frog b3galt2 (85% identical), zebrafish b3galt2 (67% identical), Drosophila melanogaster brn (20% identical), Caenorhabditis elegans bre-5 (16% identical), and 2 more. Paralogues in human: B3GALT1 (36% identical), B3GALT5 (27% identical), B3GALNT1 (24% identical), B3GNT7 (24% identical), B3GNT6 (24% identical), B3GNT2 (23% identical), B3GNT5 (23% identical), B3GNT4 (22% identical), B3GNT3 (21% identical), B3GNT9 (21% identical), B3GALNT2 (20% identical), B3GALT4 (20% identical), and 3 more.
Diseases named in the same sentence as B3GALT2 in open-access papers:
B3GALT2 is named in the same sentence as 8 diseases in open-access papers, as found by Europe PMC text mining. Sharing a sentence is not in itself a finding about the gene and the disease. The quoted sentences say what the papers report.
diabetic nephropathy (1 paper, 2021). "According to previous studies, B3GALT2 was previously shown to be downregulated in a mouse model of diabetic nephropathy, and CDH6 was upregulated in renal fibrosis mice." (PMID 34332599, 2021).
ovarian tumor (1 paper, 2023). "We observed 24 ABH antigen synthesis‐related genes in which five genes (FUT1, FUT2, FUT3, B3GNT3, and B3GNT2) were up‐regulated and three genes (ST3GAL3, ST3GAL4, and B3GALT2) were down‐regulated in ovarian tumor tissue versus adjacent tissues in all samples." (PMID 36415180, 2023).
cancer (2 papers, 2017 to 2021). A tumor composed of atypical neoplastic, often pleomorphic cells that invade other tissues. "B3GALT2 is applied to form a prognostic biomarker of carcinoma-associated fibroblasts in NSCLC." (PMID 34787244, 2021). "SKOV3 displayed strong expression of B3GALT5 and very weak expression of B3GALT1 and B3GALT2, consistent with the meta-analysis of the Cancer Cell Line Encyclopedia (CCLE)." (PMID 28167527, 2017).
tumor (2 papers, 2021 to 2023). "The expression level of CCL20, F2, GNPNAT1 and NT5E in the tumor samples was significantly higher than that in normal tissues, while the expression level of B3GALT2, and VSIG2 displayed an opposite expression pattern." (PMID 34787244, 2021). "In tumor tissues, the expression of ST3GAL6 was found to be notably reduced, whereas the expression levels of B3GALT2, ABO FUT3, B3GNT3, and B3GNT5 were observed to be significantly elevated." (PMID 37781041, 2023).
B3GALT2 also shares sentences with these, for which no sentence is quoted: E. coli infection (1 paper); infection (1); mucopolysaccharidoses (1); renal fibrosis (1).